KRTAP10-7 (keratin associated protein 10-7)
Description:
In the hair cortex, hair keratin intermediate filaments are embedded in an interfilamentous matrix, consisting of hair keratin-associated proteins (KRTAP), which are essential for the formation of a rigid and resistant hair shaft through their extensive disulfide bond cross-linking with abundant cysteine residues of hair keratins. The matrix proteins include the high-sulfur and high-glycine-tyrosine keratins.
Synonyms: KAP10.7; KRTAP18-7; KAP18.7
Tractability: No criterion of Open Targets' tractability assessment is met for any kind of drug.
Gene: Protein-coding gene on chromosome 21 (44,600,597 to 44,602,174, forward strand). Ensembl gene ENSG00000272804.
Pathways (Reactome):
Developmental Biology: Keratinization
Gene Ontology:
Molecular function: identical protein binding; protein binding
Cellular component: cytosol; keratin filament
Genetic constraint (gnomAD): Loss-of-function variants: 0 observed, 1.04 expected, observed/expected ratio (o/e) 0, 90% interval 0 to 1.71. That is too few expected variants to judge how well the gene tolerates losing a copy. Missense variants: 394 observed, 461.72 expected, observed/expected ratio (o/e) 0.85, 90% interval 0.79 to 0.93. Synonymous variants: 162 observed, 187.79 expected, observed/expected ratio (o/e) 0.86, 90% interval 0.76 to 0.98.
Homologues: Paralogues in human: KRTAP10-4 (87% identical), KRTAP10-6 (69% identical), KRTAP10-11 (64% identical), KRTAP10-9 (64% identical), KRTAP10-5 (60% identical), KRTAP10-12 (56% identical), KRTAP10-1 (55% identical), KRTAP10-2 (54% identical), KRTAP10-10 (53% identical), KRTAP10-3 (49% identical), KRTAP10-8 (49% identical), KRTAP16-1 (29% identical), and 35 more.